IL10 (interleukin 10)
Diseases named in the same sentence as IL10 in open-access papers (continued):
Sharing a sentence is not in itself a finding about the gene and the disease.
influenza (continued). "Similar to our recently reported findings in the murine influenza infection model, we noted minimal IL-10 secretion in RSV infected Rag1-/- mice and localized IL-10 production by effector T cells in the infected lungs using the IL-10 reporter Vert-X mice for infection." (PMID 21829368, 2011). "To further investigate the effect of rm-APC treatment on the inflammatory response in severe influenza, we determined pulmonary levels of various cytokines (TNF-α, IL-1β, IL-6, IL-10, IL-12p70, IFN-γ) and chemokines (KC, MIP-2) in lung homogenates obtained 48 and 96 hours after infection." (PMID 20398279, 2010). "IL-10 levels increased notably following infection; direct evidence for ATII-intrinsic IL-10 production in influenza remains limited, we hypothesize ATII can secrete IL-10, as part of their regulatory function to communicate with macrophages and help balance the inflammatory response." (PMID 41502560, 2025). "IL-10 exerts anti-inflammatory effects in monocytes, and its elevation may suppress IL-6 and TNF-α production, contributing to the diminished immune response to influenza vaccination observed in older adults." (PMID 39591191, 2024). "In this study, we observed that B.dorei administration decreased production of several cytokines (IL-1β, IL-6, IL-10,TNF-α, MCP-1, and IP-10) in lung and serum induced by influenza infection, which may alleviate excessive inflammatory response and ameliorate immunopathologic damage." (PMID 35154087, 2021). "This suggests a homeostatic level of IL-10 which does not induce too strong of an initial inflammatory response—but is still strong enough to prevent excessive tissue damage —is ideal for host protection in influenza infection." (PMID 32974217, 2020). "Interestingly, Treg and IL10 induction occurred in the absence of influenza infection indicating that early life exposure to EPFRs activates a non-specific immunosuppressive environment in the lungs." (PMID 28086957, 2017). "Since we observed an initial increase in IL10 at 1 dpe which peaked at 6 dpi, we studied whether external rIL10, if administered to Air-exposed neonatal mice would recapitulate the EPFR induced exacerbation of influenza disease severity." (PMID 28086957, 2017). "In addition, in the absence of IL-27 signaling, IL-10 production during influenza infection is attenuated." (PMID 25651926, 2015). "However, influenza infection of monocytes did not induce production of IL-10, IL-12 or IL-33 (data not shown)." (PMID 22238612, 2012). "Furthermore, IL-10–producing neutrophils in cattle modulate inflammation during parasitic infections and may similarly attenuate IFN-γ- and TNF-α-mediated lung pathology during influenza infection." (PMID 40872830, 2025). "Furthermore, we observed no significant changes in the IL-10 levels, which may have been influenced by the timing of inflammatory cytokine changes during influenza progression and differences in viral strains." (PMID 39410114, 2024). "Thus, any adjuvant alone could be equally effective in modulating inflammatory responses of γ-inactivated influenza vaccine, but only the co-administration of CCL21 and Poly (I:C) significantly reduced the numbers of IL-10-producing cells in the lung after lethal viral challenge." (PMID 34627297, 2021). "Analysis of IL10 levels in whole lung homogenates over the course of the exposure to EPFRs revealed an early (1 dpe) increase that returned to baseline levels by 4 dpe (prior to influenza infection) and remained at baseline unless mice were infected with influenza (data not shown)." (PMID 28086957, 2017). "The results showed that influenza infection induced significantly higher mRNA expressions of IL-1β, IL-6, TNF-α, IL-10, MCP-1, IP-10, IFN-γ, and IFN-β in lung compared with non-infection mice." (PMID 35154087, 2021).
lung carcinoma (188 papers, 1998 to 2026). "Our literature mining also supports a role for the decoy inhibitory protein, IL-18BP as being a mediator of lung cancer risk as well as IL-10, IL-12, IL-4 and TNF31." (PMID 38527997, 2024). "The average IL-10 value in MPE caused by lung cancer is lower than that in TPE, but tends to be higher than that in transudative pleural effusion." (PMID 39003443, 2024). "IL-10 showed a modest association with lung cancer risk, with an odds ratio of 1.30 (95% CI: 0.98–2.02, p = 0.066) for patients with levels above 13 pg/mL." (PMID 37373957, 2023). "Elevated levels of IL-10 have been observed in patients with lung cancer and it has been found to be associated with poor prognosis." (PMID 37444523, 2023). "Further studies are needed to investigate the diagnostic potential of IL-10 in larger patient populations and to determine its clinical utility for early lung cancer diagnosis." (PMID 37444523, 2023). "At the same time, we also find that IL-10 concentration was negatively associated with CB in lung cancer patients after second cycle of immunotherapy." (PMID 36091125, 2022). "Here we combined the interleukin 10 (IL-10) and oncolytic adenovirus Ad-hTERT to treat lung cancer and explored the underlying mechanism under combination therapy." (PMID 33717103, 2021). "Polymorphisms in the IL-10 gene promoter region are associated with susceptibility to a variety of cancers (including lung cancer)." (PMID 34079469, 2021). "In lung cancer, tumor growth and patient survival is closely linked to the IL-10/JAK1 axis activation." (PMID 32477352, 2020). "For instance, IL-6 was associated with poorer survival in both African-American and White lung cancer patients, while IL-10 and IL-12 were associated with poorer survival only among African-American lung cancer patients." (PMID 31448052, 2019). "Several reports have indicated that IL-10 promoter polymorphisms are related with various cancer risks including lung cancer." (PMID 29732034, 2018). "In conclusion, this meta-analysis suggested an association between IL-10 gene polymorphisms and cancer risk in the Chinese population, especially for lung cancer, colorectal cancer and low quality studies." (PMID 28977953, 2017). "In the case of IL-10, the alleles IL-10-1082G, IL-10-819C, and IL-10-592 have been observed in lung cancer patients, suggesting a predictive value." (PMID 27445423, 2016). "A recent study revealed that two IL-10 polymorphisms (-592C/A and -819C/T) show a significant association with the risk of developing lung cancer." (PMID 27445423, 2016). "Nevertheless, it has been reported that IL-10 and IL-6 polymorphisms increase the level of these proteins in serum, which correlates with higher number of cases of lung cancer." (PMID 27445423, 2016). "In lung carcinomas, IL-10 inhibits tumor cell susceptibility to cytotoxic T-lymphocyte-mediated killing." (PMID 27375834, 2016). "The role of CIP2A in mediating interleukin-10 effect in the progression of human papillomavirus (HPV)-associated lung cancer has been recently studied." (PMID 25015035, 2014). "Many case-control studies have indicated an association of IL-10 promoter polymorphisms (SNPs) with human cancer risks, including risk of lung cancer." (PMID 22848356, 2012). "Tumor immune surveillance studies have revealed an association between IL-10 and the development of human cancers such as large B-cell lymphoma, T-cell non-Hodgkin lymphoma, and colon, prostate, breast, gastric, myeloma, and lung cancers." (PMID 22848356, 2012). "The potential importance of IL-10 in cancer progression is supported by reports of an association between high IL-10 levels in serum or in tumors and worse survival in lung cancer patients." (PMID 21595995, 2011). "Impaired production of Th1-like cytokines and/or enhanced expression of Th2-like cytokines and IL-10 has been associated with tumor progression in a variety of malignancies, including lung cancer." (PMID 18801189, 2008).
lung carcinoma (continued). "Additionally, heightened levels of cytokines, including IL-1β, IL-10, and TNFα, have been linked to an increased risk of lung cancer within the AA population." (PMID 38791954, 2024). "However, the diagnostic accuracy of IL-10 for lung cancer is limited by its low specificity, as elevated IL-10 levels have also been observed in patients in other cancerous and non-cancerous conditions." (PMID 37444523, 2023). "In lung cancer, IL-10 is thought to suppress the inflammatory macrophage-Th17 cell axis, which is critical to tumourigenesis, and may be used to prevent lung cancer in high-risk patients." (PMID 34930387, 2021). "Increased IL-10 mRNA expression is associated with the advanced lung cancer." (PMID 34079469, 2021). "In lung cancer cases, some reports have indicated that loss of IL-10 in lung tumors may promote tumor progression and result in poor clinical outcomes in patients; however, an opposite effect has been reported in other studies." (PMID 22848356, 2012). "In the context of lung cancer, Gal1 has been found to induce IL-10 production in monocytes and monocyte-derived DCs." (PMID 40507367, 2025). "IL-6, IL-7, IL-10, and IL-17A levels were elevated in the plasma of lung cancer patients as compared to those in healthy controls; thus, indicating higher concentrations of inflammatory mediators in patients." (PMID 40040705, 2025). "Upregulation of IL-10 was also observed in tumour-infiltrating DCs of human lung cancer samples and in mice transplanted with lung cancer cells." (PMID 40507367, 2025). "A significant reduction in IL-10-producing, tumour-infiltrating DCs and lung cancer incidence was evident in mice harbouring Gal1-silenced tumour cells, emphasizing that Gal1 is a potential target for the development of lung cancer therapeutics." (PMID 40507367, 2025). "The combined use of specific cytokines showed promise in diagnosing lung cancer, with IL-8, IL-10, and MCP-1 achieving 76% sensitivity and 79% specificity in AAs, and IL-6 and IL-8 combined offering 76% sensitivity and 74% specificity in WAs." (PMID 38276239, 2024). "IL-10 and MCP-1 exhibited pronounced elevation specifically in AA lung cancer patients, with MCP-1 being associated with lung adenocarcinoma." (PMID 38276239, 2024). "Single nucleotide polymorphisms (SNPs) in several cytokines, such as IL1B, IL-1RN, and IL-10, exhibited significant correlations with fatigue levels in survivors of lung cancer." (PMID 39564104, 2024). "The combined use of specific cytokines showed promise in lung cancer diagnosis, with IL-8, IL-10, and MCP-1 achieving 76% sensitivity and 79% specificity in AAs and IL-6 and IL-8 combined offering 76% sensitivity and 74% specificity in WAs." (PMID 38276239, 2024). "The ROC plot analysis revealed that IL-1b, IL-2, IL-6, IL-10, IL-12p70, and TNF-alpha had a significant association with lung cancer, although with relatively low discriminative performance." (PMID 37373957, 2023). "Interleukin-10 (IL-10) is a cytokine that has been investigated as a potential biomarker for lung cancer." (PMID 37444523, 2023). "The correlation between IL-10 and S100A9 gene expression in lung cancer was analyzed using the Gene Expression Profiling Interactive Analysis database, and it showed a positive correlation between IL-10 and S100A9 (R = 0.4, P < 0.001)." (PMID 37533789, 2023). "In human lung cancer, tumor-associated macrophages secrete TNF-α, IL-10, and IFN-γ, which induce B7-H4 expression in lung cancer cells." (PMID 35410218, 2022). "In terms of protein expression level, the level of IL-10 in lung cancer tissue of the CON group was significantly higher than that of the Saline group (P<0.01)." (PMID 36186906, 2022). "We found that lung cancer tissue had significantly higher levels of IL-10 protein than healthy lung tissue, and HIIT also up-regulated the level of IL-10 in lung cancer tissue." (PMID 36186906, 2022).
lung carcinoma (continued). "We now report that as with Mef2d, the deletion of Mef2c in Tregs switches off the expression of Il10 and Icos and leads to enhanced antitumor immunity in syngeneic models of lung cancer." (PMID 34290714, 2021). "Th1 (IFN-γ) or Th2 (IL-4 and IL-10) cytokines responsible for M1 or M2 macrophage polarization were detected in malignant pleural effusions of lung cancer patients in a previous study." (PMID 33175182, 2021). "Some evidence pointed to the inhibitory role of IL-10+ Bregs (Regulatory B-cells) in human lung cancer, especially in ADC." (PMID 34336101, 2021). "Increase in IL-6, IL-10, NLR, PLR, and LDH levels or reduced ALC and ALB levels were associated with the occurrence of CIP in lung cancer patients." (PMID 34327140, 2021). "Exosomal TGF‐β and IL‐10 from metastatic lung cancer promoted cell migration under hypoxic conditions." (PMID 33508878, 2021). "Tim-3+ Treg cells were found to present much more tumor immunosuppression than Tim-3- Treg cells in lung cancer patients, with the secretion of IL-10 and granzymes." (PMID 33936081, 2021). "Many patients with malignant tumors, including lung cancer, have elevated serum and peritumoral IL-10 levels." (PMID 34079469, 2021). "We demonstrated that the levels of IL-2, TNF-α, and IL-10 in the plasma from lung cancer patients were significantly higher than those in the plasma from healthy donors." (PMID 32788875, 2020). "Expression of CCL2, CCR2 or in combination with IL6 and IL10 correlates with a worse prognosis in lung cancer patients." (PMID 32219066, 2020). "The M2 macrophages secrete IL-10 in the extracellular media which binds to the IL-10RA, causing the activation of JAK1, STAT1, STAT3, STAT6, NF-κB, and Notch in lung cancer cells." (PMID 32477352, 2020). "On the other hand, TAMs-derived IL10 level showed consistent prognostic significance in lung cancer patients." (PMID 32219066, 2020). "Other observations include a decrease in IL-10 cytokine production and stimulation of IL-12 cytokine expression, apoptosis reduction, and suppression of lung cancer." (PMID 32962026, 2020). "IL10 also drives in vivo lung cancer growth and metastasis by upregulating the CCL2/C-C motif chemokine receptor 2 (CCR2) and C-X-C motif chemokine ligand (CXC3CL1)/C-X3-C motif chemokine receptor 1 (CX3CR1) axis in macrophage-tumor cell crosstalk." (PMID 32219066, 2020). "We observed that collected media from Ab-treated cells were able to revert TAM phenotype induced by lung cancer spheroids as indicated by a decrease of IL-10 and an increase of IL-6 and IL-12 (the latter was observed only after moAb treatment)." (PMID 33123122, 2020). "In lung cancer for instance, certain cytokines (IL-4, IL-5, IL-8, IL-10, IFN-γ, and TNF-α) were significantly elevated among EA compared to AA patients, whereas elevated IL-1β, IL-10, and TNF-α levels were associated with lung cancer only among AA patients." (PMID 32714862, 2020). "Consistent with previous studies, AS ameliorated cancer-associated inflammation, decreased the expression of inflammatory factors such as TGF-β and IL-10, and suppressed M2 macrophage polarization when administered to treat lung cancer." (PMID 32595723, 2020). "In their turn, M2 macrophages secrete both pro-(IL-6) and anti-inflammatory cytokines (IL-10) with oncogenic potential that sustain the EMT of lung cancer cells, through downregulation of E-CAD and upregulation of VIM, N-CAD." (PMID 32477352, 2020). "The level of CD4+CD25+CD127-Tregs in peripheral blood of patients with lung cancer is positively correlated with plasma IL-10 level." (PMID 32218692, 2020). "PRE-084 has been shown to promote tumor growth in a syngeneic lung cancer (L1C2 murine alveolar cell carcinoma) model in part by inducing IL-10 at the tumor site." (PMID 31695608, 2019).
lung carcinoma (continued). "For example despite circulating IL-10 levels have been associated with poor patient prognosis in a number of cancer settings, yet IL-10 expressing CD8 T cells confer a positive prognosis in patients with lung cancer." (PMID 30631766, 2018). "Tobacco contains carcinogens such as NNK (nicotine-derived nitrosamine ketone) that makes induction of lung cancer by changing the stimulation of IL-10 expression." (PMID 29732034, 2018). "Among 59 lung cancer patients, 27 patients exhibited higher IL10 levels, whereas the remaining 32 patients showed unaltered IL10 levels in their lung tumor tissues." (PMID 26956044, 2016). "IL-10 has been reported to be found at high levels in a variety of human malignancies, including lung cancer." (PMID 27833081, 2016). "In the lung tumor tissues, IL10 accumulated in the epithelial cells and CD68+ macrophages, suggesting that IL10 from cancer cells and tumor-associated macrophages is involved in lung cancer progression." (PMID 26956044, 2016). "Knocking out IL10 in these two mice prevented lung cancer formation and provided direct evidence for the role of IL10 in lung cancer formation." (PMID 26956044, 2016). "Here, we found that increased IL10 levels are correlated with a poor prognosis in lung cancer patients." (PMID 26956044, 2016). "Because the inhibition of JAK1/STAT3 signaling exhibits potent tumor-suppressive effects on lung cancer, it is important to study how IL10 induces JAK1/STAT3 signaling in cancer development." (PMID 26956044, 2016). "Addition of recombinant human IL-10 (rhIL-10) attenuated the effect of laricitrin on the amelioration of DCs’ inadequate differentiation induced by lung cancer." (PMID 27833081, 2016). "Analyzing the relationship between IL10 levels and lung cancer progression, we found that late-stage patients showed higher IL10 expression and patients with higher IL10 levels presented lower survival rates." (PMID 26956044, 2016). "IL10-deficient Kras4bG12D- and EGFRL858R-induced lung cancer mice (Scgb1a1-rtTA/TetO-Kras4bG12D/IL10−/− and Scgb1a1-rtTA/TetO-EGFRL858R/IL10−/−) were established for this purpose." (PMID 26956044, 2016). "This study demonstrates that laricitrin provides the highest level of efficacy to improve lung cancer-mediated DC suppression through the down-regulation of the STAT3/IL-10 signaling pathway." (PMID 27833081, 2016). "IL-10 mRNA levels in peripheral B cells were significantly higher in lung cancer patients as compared with healthy controls." (PMID 27605397, 2016). "In summary, the present data reveal that the peripheral B cells of lung cancer patients express low levels of miR-98 and high levels of IL-10." (PMID 27605397, 2016). "To understand the role of IL10 in lung cancer, we studied IL10 levels in normal and lung tumor tissues." (PMID 26956044, 2016). "Some cytokines have two opposite effects in lung cancer progression, according to the molecular context, which is the case for IL-10 and TNF-α." (PMID 27445423, 2016). "Increased serum and peritumoral IL-10 levels have been reported in several malignancies, including lung cancer, suggesting a role for IL-10 in the tumor escape from the immune response." (PMID 27375834, 2016). "In summary, these results from clinical cohorts and animal models show that IL10 levels were highly upregulated in lung cancer tissues and correlated with a poorer patient prognosis." (PMID 26956044, 2016). "Syk was responsible for TREM-2-mediated inhibitory signaling in lung cancer while Syk inhibitor restrained the IL-10 production of TREM-2+DC." (PMID 27102437, 2016). "Laricitrin also prevented the effects of lung cancer cells on IL-12 inhibition and IL-10 induction in DCs." (PMID 27833081, 2016). "The data indicated that the IL10 levels in the sera of the lung cancer patients (38.16 pg/mL) were significantly higher than that in the normal individuals (32.55 pg/mL)." (PMID 26956044, 2016).